CD44 (CD44 molecule (IN blood group))
Diseases named in the same sentence as CD44 in open-access papers (continued):
Sharing a sentence is not in itself a finding about the gene and the disease.
tumor (5,040 papers, 1995 to 2026). "Validation in patient-derived metastatic liver tissues confirmed elevated hepatic MIF expression and increased CD44-positive tumor cells in MASLD-associated PDAC cases." (PMID 41545340, 2026). "We put special emphasis on the role of CD44 and its variant isoforms (CD44v), which play a role in the interface of cancer stemness, tumour microenvironment crosstalk, modulation of epithelial-mesenchymal transition (EMT), chemoresistance, and metastasis." (PMID 41751352, 2026). "A T‐PC metacluster marked by CD44 is shown to promote M2 polarization of tumor‐associated macrophages and tumor growth." (PMID 41001759, 2025). "Our group also developed a cancer-targeted nanoassembly responsive to CD44 and tumor-associated enzymes within the TME that released protoporphyrin IX into the blood as a synthetic biomarker." (PMID 41375132, 2025). "The incidence and frequency profile of CD44 variant exons expression in several tumor types, including the most common and those associated with the highest mortality." (PMID 40114966, 2025). "Contrastingly, Orientin treatment caused reduction in the CD44+/CD133+ cells suggesting presence of a smaller number of CSCs within the tumor of this group." (PMID 40045186, 2025). "Although CD24 expression is linked to aggressive tumor behaviour, in vitro gastric CSCs typically exhibit a CD44-positive/CD24-low phenotype." (PMID 40866457, 2025). "CD44-deficient CTLs exhibit reduced migration rates in tumors and impaired ability to resume migration after contact with tumor cells, leading to decreased screening efficiency and potentially compromising tumor cell clearance." (PMID 40995371, 2025). "Abnormal splicing and dysregulation of CD44 isoforms have been linked to tumor progression and resistance to therapy, highlighting their significance in cancer biology." (PMID 40363706, 2025). "Additional research is required to ascertain the precise prognostic significance of the CD44 marker, an effective therapeutic approach that aims to eliminate cancer stem cells by targeting these cells, as it has an increased risk of tumor recurrence." (PMID 40881916, 2025). "We found that a T‐PC metacluster marked by CD44 expression demonstrated a close association with tumor‐associated macrophages (TAMs) in bioinformatic analyses." (PMID 41001759, 2025). "Among those upcoming tumor-specific targets, the CD44 AS isoform CD44v6 has been implicated in LUAD tumorigenesis, invasion, and metastasis." (PMID 40282505, 2025). "Several studies have shown that CD44+/CD24− tumor cells represent a poor prognosis factor associated with more aggressive outcomes." (PMID 40430044, 2025). "CD44 is a surface molecule whose expression is described on several tumour entities and is associated with reduced survival." (PMID 41168417, 2025). "In CAFs, PIAS1+ cells showed downregulation of immunosuppressives MIF–CD74_CD44 signaling and upregulation of tumor-suppressive CD99–CD99 interactions associated with immune activation." (PMID 40941002, 2025). "Taxanes (paclitaxel/docetaxel) combinations frequently diminish tumor-associated stem-cell populations (CD44+/CD24−), decreasing resistant fractions and improving tumor control." (PMID 41303508, 2025). "High protein expression levels of HCC CSC markers, such as CK19, CD133, and CD44, are strongly linked to tumor angiogenesis and a poor prognosis for patients with HCC." (PMID 40890130, 2025). "Further investigation of CD44, closely associated with tumor invasion and metastasis, revealed higher levels in the PBS group but limited expression in the PPMAD plus laser group." (PMID 40110052, 2025). "TNFRSF8 (CD30) and CD44 are associated with modulating macrophage activity and promoting tumor migration and invasion, respectively." (PMID 41153362, 2025). "CD44, a cell surface transmembrane glycoprotein, is known to regulate tumor progression and cancer-associated molecular signaling pathways." (PMID 40114966, 2025).
tumor (continued). "CD44 variants (CD44v) play essential roles in the promotion of tumor metastasis, maintenance of cancer stem cell properties, and resistance to treatments." (PMID 41009730, 2025). "CD44 is a transmembrane glycoprotein commonly associated with various cancers, where it plays a critical role in tumour invasion and metastasis." (PMID 39316249, 2025). "CD44, a cell surface glycoprotein, has been implicated in cell-cell interactions, migration, and tumor metastasis." (PMID 39833941, 2025). "Despite their role in tumor classification, CD44 variants play a critical role in maintaining CSC populations, which are inherently resistant to chemotherapy and radiation." (PMID 40363706, 2025). "In cancer-associated fibroblasts and tumor-associated macrophages, this same CD44/integrin–PI3K/AKT axis sustains cell survival, motility, and immune regulatory functions, underscoring its central role in tumor progression and therapeutic resistance." (PMID 41391064, 2025). "Dysregulation of CD44 expression is closely associated with tumor proliferation, invasion, metastasis, and therapeutic resistance." (PMID 40240758, 2025). "It is considered a tumor metastasis-related gene, with the CD44 variant containing exon V6 being the most closely related to tumor invasion and metastasis." (PMID 40361513, 2025). "In BCSCs, CD44 expression is associated with tumor self-renewal, tumorigenesis, adhesion, invasion, and metastasis." (PMID 40635786, 2025). "CD44 is closely related to tumor invasion and metastasis and is considered to be a tumor metastasis-related gene, among which the CD44 variant containing exon V6 is most closely related to tumor invasion and metastasis." (PMID 40361513, 2025). "It has been demonstrated that combining ASCL1 with markers such as OTP, HNF1A or CD44 improves NETs subclassification, with identifying groups linked to clinical characteristics, including patient sex and tumor location." (PMID 41196447, 2025). "Tumor cells were defined as EpCAM+ CD90− CD140a− CD45− CD33− CD14− and further analyzed for the expression of CD24 and CD44, two markers associated with tumor aggressiveness and stem-like features." (PMID 40877861, 2025). "CD44 associated with tumor-derived EVs has been linked to cancer progression, particularly premetastatic niche formation and metastasis." (PMID 40182121, 2025). "CD44, a well-established stem cell marker, facilitates tumor metastasis by inducing the loss of E-cadherin and accumulation of β-catenin." (PMID 41156387, 2025). "Proteolytic cleavage of membrane-bound CD44 generates a soluble form of CD44 that enters biological fluids and reflects dynamic tumor-associated processes such as proliferation, invasion, and extracellular matrix remodeling." (PMID 41440277, 2025). "ESRP1 can indirectly affect the activity of these pathways by regulating the expression of CD44 splice variants, thereby influencing tumor growth, invasion, and drug resistance." (PMID 40046628, 2025). "CD44/HCAM (homing cell adhesion molecule) expression is associated with tumor growth and metastasis and is a potential marker for cancer stemness and poor prognosis in HNSCC55,56." (PMID 40624315, 2025). "This study demonstrated that high CD44 expression is associated with metastasis to lymph nodes and distant metastasis, poorer survival of the patients, tumor recurrence, higher tumor stage and grade and aggressive clinicopathological features." (PMID 40738059, 2025). "The variant isoforms of CD44 (CD44v) have been implicated in multiple oncogenic processes, including the promotion of tumor invasion and metastasis, acquisition of cancer stem cell (CSC) properties, and resistance to chemotherapy and radiotherapy." (PMID 41009730, 2025). "The β-catenin-target gene, Cd44, is a marker of cancer stemness and has been implicated in tumor invasion." (PMID 40399276, 2025).
tumor (continued). "Pterostilbene reduced the percentage of CD44+/CD24− MDA-MB-321 cells cocultured with tumor-associated macrophages, as well as the migratory and invasive properties of MDA-MB-231 cells." (PMID 40687439, 2025). "Bioinformatic analyses on integrated in‐house and public scRNA‐seq data have found a T‐PC metacluster marked by CD44 closely associated with tumor‐associated macrophages (TAMs)." (PMID 41001759, 2025). "In this study, we investigate the molecular mechanisms underlying these substantial changes in tumor properties following CD44 kd." (PMID 40438109, 2025). "These cells stimulated immunosuppression and tumor-associated macrophage (TAM) differentiation by interacting with macrophages via MIF-(CD74+CD44) signaling." (PMID 40936936, 2025). "CD44 mediated internalization of HA and covalently linked cargo molecules by tumor lines RT-4 and RT-112/84." (PMID 39851489, 2025). "Low expression of ESRP1 leads to an increase in CD44s levels and a decrease in CD44v (variant CD44) levels, both of which play crucial roles in tumor development." (PMID 40046628, 2025). "Loss of OTP has also been linked to decreased CD44 expression, a cell adhesion molecule involved in tumor suppression and differentiation." (PMID 41196447, 2025). "Aberrant splicing of genomic loci, including those encoding estrogen receptors (ERs), HER2/neu, Cyclin D1, BRCA1, BARD1, Tenscin-C, and CD44, has been implicated in breast carcinogenesis." (PMID 40563429, 2025). "Co-expression and interactions between SPP1+ tumor-associated macrophages (TAMs) and regulatory T cells (Tregs) have been identified within CD44-enriched regions in the TME." (PMID 41425545, 2025). "Given the role of CD44 in promoting tumor resistance, targeting CD44 and its associated pathways has emerged as a promising strategy for overcoming MDR." (PMID 40363706, 2025). "The P-value was 0.002, indicating a highly statistically significant association between CD44 expression and tumor size." (PMID 40881916, 2025). "RNA interference approaches have also shown promise in silencing CD44 variants, leading to reduced tumor growth and enhanced sensitivity to chemotherapeutics." (PMID 40363706, 2025). "CD44 and CD44 variants have been observed on tumor EVs derived from gastric, ovarian, and pancreatic cancer cell lines and to cause tumorigenesis and metastasis." (PMID 40182121, 2025). "The relationship between dysplasia grade and reduced CD44 expression was linked to key biological processes, including proliferation, cell differentiation, motility, and tumor invasion." (PMID 40005368, 2025). "In TNBC, CD44 overexpression is associated with a more aggressive tumor phenotype, where it acts as a key regulator of proliferation, invasion, chemoresistance, and tumor relapse." (PMID 40342488, 2025). "Previous studies have shown that CD44 interaction with matrix hyaluronan (HA) activates microRNAs (miRNAs) signaling pathways associated with tumor progression, invasion, and chemoresistance." (PMID 40438109, 2025). "This suggests a specific link between the loss of the CD44 expression program and the overall tumor stage, a key determinant of prognosis." (PMID 41514534, 2025). "In LUAD, specific CD44 splicing patterns have been associated with tumor grade, stage, and patient survival." (PMID 40282505, 2025). "Specifically, CD44v6 overexpression correlated with higher tumor stage, and both CD44 and CD44v6 (as well as CD44v8-10) were linked to poor outcomes and increased risk of recurrence." (PMID 41514534, 2025). "The cell surface glycoprotein CD44, a known marker of cancer stem cells, is similarly associated with higher tumor grade and poorer 5-year survival." (PMID 40429363, 2025). "The complex regulation of alternative splicing of CD44 pre-mRNA into many different variants has been the object of several studies, mostly in tumor cells." (PMID 40943148, 2025).
tumor (continued). "Following stimulation, the percentage of CD8+ T cells expressing IFNγ or CD44 was similar in young and old mice, suggesting that tumor-associated T cells from both age groups can be activated at similar levels." (PMID 41332581, 2025). "In PCa, a high expression of CD44 is linked to cancer stem cell-like properties, tumor aggressiveness, recurrence, and poor prognosis." (PMID 40141159, 2025). "CD44 is a transmembrane glycoprotein and its overexpression in tumor stem cells is associated with the occurrence and development of tumors." (PMID 40240758, 2025). "The association of CD44 variant exon expression levels with tumor response to chemotherapy in animal studies." (PMID 40114966, 2025). "The same was observed for mmp2 and mmp9, metalloproteases connected to tumor cell invasion, for glucose-phosphate isomerase 1 (gpi1), tnfα, lysyl oxidases (lox, loxl), and the progenitor marker cd44 that is also linked to increased metastasis." (PMID 39095583, 2024). "CD44 has also been found to be expressed by several cells in the tumor stroma including cancer-associated fibroblasts (CAFs) and endothelial cells." (PMID 38796656, 2024). "CD44 also showed a connection with tumor mutational burden (TMB) and MSI, indicating its potential as an emerging biomarker for predicting responses to immunotherapy." (PMID 38672650, 2024). "CD44 has been reported to be related to tumor invasion, and in gastric and CRCs, proteins expressed from CD44 variant exon 6 or exon 9 have been reported to be involved in hematogenous metastasis." (PMID 38672639, 2024). "In agreement with the literature data, we found a positive association between increased CD44 expression in tumor stroma with a higher number of microvessels, suggesting a role for CD44 in neoangiogenesis." (PMID 38796656, 2024). "The cancer stem cell marker CD44 characterizes a tumor subpopulation highly associated with tumor metastasis and radioresistance in EC patients, ultimately leading to tumor recurrence." (PMID 38727811, 2024). "LMO7 was involved in tumor-intrinsic innate immunity and immune evasion, while CD44 was associated with cancer stem cells and exhibits spliced variants that contribute to cancer progression." (PMID 39704173, 2024). "One of the most commonly studied markers for cancer stem cells, CD44 has been strongly implicated in both tumor initiation and metastasis." (PMID 38240752, 2024). "Within the realm of tumor biology, CD44 is closely associated with the progression and metastatic potential of cancer cells." (PMID 39339402, 2024). "CD44 was found to be significantly associated with high tumor grade, advanced stage, high mitotic count, poor tumor differentiation, and OS." (PMID 39148690, 2024). "The risk score was positively related to CD44 expression, suggesting that it is a good marker to detect tumor stemness." (PMID 38221614, 2024). "MUC5AC exerts its effects by interacting with various transmembrane-associated proteins, including CD44, integrin β4, and integrin β5, during different tumor events." (PMID 38825648, 2024). "KO of CD44 in the tumor cells also caused deceases of the Cy5.5 signals in tumors in both WT and CD44−/− mice but to a much lesser extent." (PMID 38177179, 2024). "CD44 interaction with Hyaluronic acid (HA), one of the major GAGs that is extensively studied in cancer, has been associated with tumor cell proliferation and enhancing chemo resistance via regulating PI3K/Akt and MAPK signal pathways." (PMID 38962317, 2024). "CD44 is known to be expressed on cancer stem cells and implicated in many cancers as a marker of tumor burden and metastatic potential due to its numerous variant isoforms." (PMID 38983848, 2024). "Recently, the CD44 standard isoform has been implicated in tumor progression and the metastasis cascade through microenvironment interactions." (PMID 38790166, 2024).
tumor (continued). "A recent institutional study from Damarasingu P.V. showed that a loss of positivity in poorly differentiated carcinoma and a loss of CD44 expression in lower tumor staging were associated with greater tumor aggressiveness." (PMID 39768912, 2024). "In all baseline biopsies we found the expression of at least one CD44 isoform on tumor tissue, with the different variants being often co-expressed by cancer cells and CD44v9 the most represented." (PMID 38600583, 2024). "Contrarily, it is contended that CD44s exhibit significant expression in most tissues, while CD44 variants are predominantly expressed in tumor cells." (PMID 38903413, 2024). "Recent studies have found that tumor cells with high expression of CD44 is associated with brain metastases." (PMID 38783892, 2024). "Studies have linked CD44 to different tumor cell processes, such as adhesion, migration, and metastasis." (PMID 39547513, 2024). "The results regarding loss or gain in CD44 expression are controversial in association with clinicopathological features suggesting aggressive tumor characteristics, such as a higher stage, a higher grade, and a lower survival rate." (PMID 39768912, 2024). "The relationships of the risk score and CD44 were investigated to acquire a better understanding of the role of the risk score in tumor stemness." (PMID 38221614, 2024). "We were able to show that CD44 expression presents a positive association with tumor grade and overall survival, predicting a worse patient outcome in ccRCC." (PMID 38790166, 2024). "CD44v9, one of the splicing variants of CD44, is closely associated with tumorigenicity and several cellular processes, including cell proliferation, metastasis, and tumor invasiveness through epithelial-mesenchymal transition (EMT)." (PMID 38672639, 2024). "CD44 is linked to tumor malignancy and denotes a poor prognosis for a number of cancers, including liver cancer." (PMID 39463763, 2024). "LMP1 induces the expression of CD44 on the cell surface, a molecule implicated in increased tumor growth and dissemination." (PMID 39228892, 2024). "CD105 is involved in tumor development, inflammation, and the accumulation of CAFs (cancer-associated fibroblasts), while CD44 facilitates tumor cells adhesion, migration, and chemoresistance by interacting with hyaluronic acid." (PMID 38341519, 2024). "The CD44 protein is closely associated with tumor growth, proliferation, metastasis, invasion, and angiogenesis." (PMID 39771471, 2024). "The diverse functional attributes of OPN in tumor progression are directly linked to its structural features as well as binding to specific integrins and CD44." (PMID 39062100, 2024). "Research has also indicated that positive immunohistochemical staining for CD44, Shh, and Gli1 proteins was associated with larger tumour sizes, more severe gross and histological types, and higher TNM stages." (PMID 38920995, 2024). "ITGB1+ EVs are involved in ECM interactions and metastatic niche formation, while CD44+ EVs are linked to tumor recurrence and therapy resistance in GBM, suggesting their role as biomarkers for aggressive tumor subtypes." (PMID 39594703, 2024). "The membranous model was validated in CD44-prostate, where patients with tumours with low CD44 expression was associated with shorter TTR than patients with high CD44." (PMID 39040241, 2024). "CD44 is a cell surface glycoprotein implicated in cell adhesion, proliferation and metastatic tumor growth." (PMID 39020106, 2024). "For example, CD44 expresses multiple subtypes through the AS process, and compared to wild-type, CD44 variant forms are associated with tumor development and considered as potential therapeutic targets for cancer treatment." (PMID 38734676, 2024). "Elevated expression of CD44 in tumors is associated with characteristics of tumor stem cells, cell migration, and infiltration processes." (PMID 38277205, 2024).